PAX3 (paired box 3)
Diseases named in the same sentence as PAX3 in open-access papers (continued):
Sharing a sentence is not in itself a finding about the gene and the disease.
tumor (continued). "During our analysis the most prominent differences connected with the location of the tumor were noted for the IRX2, PAX3, CXCL14, LHX2, SIX6, CNTN1 and SIX1 genes." (PMID 26497896, 2015). "The IGF1/IGF1R axis is overexpressed and constitutively phosphorylated especially in PAX3/7-FOXO1 positive ARMS cells, this being one of the major tumorigenic pathways in this tumour." (PMID 26445453, 2015). "Along these lines, we demonstrated that PAX3-FOXO1 is phosphorylated at three specific sites and that its pattern of phosphorylation is altered relative to wild-type Pax3 throughout early myogenesis and in ARMS tumor cells." (PMID 25821947, 2015). "When compared to PDGF-B injection alone, the addition of Pax3 to PDGF-B significantly reduced survival and increased tumor penetrance to 20 out of 25 mice (p = 0.0003)." (PMID 25330836, 2014). "When combined with the pro-proliferative effects of increased PDGF signaling, a common event found in PAX3-High human BSG, ectopic Pax3 enhances gliomagenesis, increasing tumor frequency and promoting progression to a high-grade malignancy." (PMID 25330836, 2014). "Down-regulation or inhibition of PAX3/FOXO1 inhibits proliferation and induces apoptosis in aRMS cells, hence the aRMS tumor cells become dependent on fusion protein expression." (PMID 23372815, 2013). "We show that PAX3 and MITF immunolabeling can be used to identify melanocytes as well as melanocytic transformed cells within a tumor bulk." (PMID 22747534, 2012). "Metastatic ARMS tumors expressed PAX3-FKHR at incrementally higher levels than the primary tumors, further demonstrating the roles of PAX3-FKHR in promoting tumor metastasis." (PMID 22533991, 2012). "Here, we have quantified the relative levels of chimaeric and wild-type PAX transcripts in various subtypes of RMS (n=34) in order to assess the relevance of wild-type PAX3 and PAX7 gene expression in these tumours." (PMID 12865925, 2003). "In histopathological analysis, the tumours resembled human ERMS, expressing low Pax3 levels, and elevated Pax7 levels, which generally mirrored c-Met expression." (PMID 12865925, 2003). "Expression of each of the wild-type PAX3 and PAX7 genes and the two fusion genes PAX3-FKHR and PAX7-FKHR was measured by quantitative real-time PCR in 34 primary RMS tumours and in three RMS cell lines." (PMID 12865925, 2003). "The multimodal treatment strategies for this tumor are based on a specific risk stratification system that not only considers the TNM system, but also histology, fusion status (PAX3 or 7/FOXO1), anatomical site (favorable vs. unfavorable), size, and age." (PMID 41025537, 2026). "As the MR2 subset contains Pax7 lineage tumours both with and without Pax3::Foxo1 knock‐in, these findings further reinforce the notion that the functional and epigenetic impact of Pax3::Foxo1 in the Pax7 lineage is very limited." (PMID 39812007, 2025). "Finally, tumours in MR2 corresponded to either Pax3::Foxo1 in the Pax7 lineage or DNA alterations other than Pax3::Foxo1 in one of three lineages (Myf6, Pax3, or Pax7)." (PMID 39812007, 2025). "Our unsupervised analyses of DNA methylation patterns in these GEMM tumours yielded two major clusters, corresponding to high and no/low expression of Pax3::Foxo1, which mirrored the results for human FP and FN RMS tumours." (PMID 39812007, 2025). "In an inducible PAX3::FOXO1 human myoblast system, the fusion-oncogene cooperated with MYCN to inhibit differentiation and promote proliferation during transformation; however, in this context, PAX3::FOXO1 is not required for tumor recurrence." (PMID 40599857, 2025).
tumor (continued). "We concluded that the ML cluster consisted of mouse tumours with high Pax3::Foxo1 expression (11/11, 100%), whereas the MR cluster consisted of mouse tumours with either no or weak Pax3::Foxo1 expression (0/20, 0%) (p < 0.001)." (PMID 39812007, 2025). "In primary localized RMS RT-qPCR showed no tumour-specific fusions (PAX3/7::FOXO1) in cfRNA at baseline, compared to 62% in primary metastatic patients." (PMID 39797974, 2025). "Two distinct methylation‐defined subsets were found for GEMM RMS tumours with no/low Pax3::Foxo1 expression: one subset enriched in Pax7 lineage tumours and a second subset enriched in myogenic factor 5 (Myf5) lineage tumours." (PMID 39812007, 2025). "PAX3::FOXO1-target genes likely have diverse pro-tumorigenic functions such as stimulating proliferation and invasion, inhibiting differentiation, and promoting cancer cell survival by repressing tumor suppressors." (PMID 40599857, 2025). "This study demonstrates that progression of tumour is delayed in pax3a/pax3b mutant embryos, and that several genes in the RAS/MAPK signalling pathway are down-regulated in the mutants, linking Pax3 transcriptional regulation to one of the main mediators of malignancy in zRMS." (PMID 36229514, 2022). "Although in these cases no prior investigation (FISH or RT-PCR) was performed, this tumor is known to be typified by gene fusions involving the PAX3 gene." (PMID 32351889, 2020). "However, if these tumours progress with ERK reactivation, the expression of PAX3, BRN2, and MITF should be restored." (PMID 30277012, 2019). "This tumour was fusion negative, showing increased copy number (up to 10 per cell) for PAX3, PAX7 and FOXO1 and displaying TFAP2B positive reaction." (PMID 31493794, 2019). "It is thus likely that the myogenic-like transcriptome of ARMS tumours is the result of PAX3:FOXO1 activation rather than a remnant of their lineage origin." (PMID 28615069, 2017). "It is important to note that in the ARMS samples examined, patient age, treatment history, tumour location and the PAX3/7-FOXO1 status likely contributed to the lack of significance observed in Staufen1 expression." (PMID 28211476, 2017). "On reverse transcriptase polymerase chain reaction (RT-PCR) analysis, tumor cells lacked Myo D1 and PAX3/7-FKHR transcripts and showed myogenin transcripts." (PMID 26208724, 2015). "On reverse transcriptase polymerase chain reaction (RT-PCR) analysis, tumor cells lacked Myo D1, PAX3/7-FKHR transcripts and showed myogenin transcripts." (PMID 26208724, 2015). "As a test of checkpoint adaptation and the permissiveness of aRMS cells to transit from G2 to mitosis despite single- and double-stranded DNA damage, we irradiated tumor cells with or without Pax3:Foxo1a knockdown." (PMID 24453992, 2014). "Of these genes, Pax3, Irx5, and Chl1 were also differentially regulated between the Olig2-compartments of BSG and CG suggesting that they represent biological differences within the tumor cells." (PMID 25330836, 2014). "Other studies focused on genes whose expression is present in PAX3-FKHR-positive tumor samples but is absent in PAX3-FKHR–negative tumor samples, however, PAX3-FKHR is not the only difference between these tumor samples." (PMID 22533991, 2012). "By contrast, PAX7 mRNA expression corresponded to translocation status rather than histological subtype, with PAX7 expression detected in both ARMS and ERMS, but mainly restricted to tumours lacking either a PAX3-FKHR or a PAX7-FKHR fusion gene." (PMID 12865925, 2003). "However, LTS progenitors can reactivate PAX3 protein expression, engraft, and contribute to muscle regeneration in vivo like normal MuSCs, without forming tumours even after 12 months." (PMID 37177849, 2023). "Furthermore, inhibition of NFκB by genetically ablating its activating kinase inhibitor, IKKβ, by conditional deletion in a mouse model harboring the Pax3:Foxo1 chimeric oncogene failed to abrogate spontaneous tumor growth." (PMID 28883017, 2017).
tumor (continued). "For the BRAFV600E;NRASQ61K culture, we did not have a paired “before” culture and hence could not assess whether PAX3 or MITF expression was increased in the culture from the acquired resistant tumor." (PMID 26977879, 2016). "In conclusion, our results demonstrated that 16 miRNAs were able to correctly classify tumors into tumor subtypes (PAX3/FOXO1-positive ARMS and translocation-negative RMS) and may be useful to diagnose RMS." (PMID 25915942, 2015). "In this model, Pax3:Foxo1a was necessary but not sufficient for aRMS tumor initiation." (PMID 24453992, 2014). "To investigate the transcriptional basis of this Pax3:Foxo1a dynamic expression, we performed QPCR of Pax3 and Foxo1 using cell cycle specific sorted C2C12 mouse myoblast cells of the genotype Pax3(wt/wt) and mouse aRMS primary tumor cells of the genotype Pax3(wt/Pax3:Foxo1a)." (PMID 24453992, 2014). "To test the acute role of Pax3:Foxo1a in tolerization to treatment-related DNA damage in vivo, we used eYFP siRNA to transiently knock down Pax3:Foxo1a in aRMS tumor cells treated with radiation versus non-irradiated controls that were then orthotopically injected into unirradiated host mice." (PMID 24453992, 2014). "PAX3 expression was detected in 16 out of 34 tumour samples, regardless of subtype or translocation status, and it seems unlikely that a ‘dose’ effect of PAX3 activity may confer a transformed phenotype in RMS in which the PAX-FKHR fusion genes do not occur." (PMID 12865925, 2003). "However, elevated PAX7 expression in ERMS is not accompanied by elevated PAX3 expression, suggesting that this tumour type is not derived from proliferating myoblasts in the dermomyotome." (PMID 12865925, 2003). "Our results indicate that TFAP2B, ALK and a novel marker OLIG2 may serve as surrogate markers for PAX3/7-FOXO1 status what is especially beneficial in cases where poor quality tumour tissue is not suitable for reliable genetic analyses or shows inconclusive result." (PMID 31493794, 2019). "Hence, in tumours without PAX3/7-FKHR fusion genes, it is possible that mechanisms other than those associated with PAX3/7-FKHR fusion genes cause increased expression of wild-type PAX genes, with the same tumorigenic outcome as expression of the chimaeric proteins." (PMID 12865925, 2003). "ENT as a single agent showed minimal antitumor activity in this embryonal model of RMS; however, in these fusion-negative (Pax3:Foxo1 non-expressing) mice, treatment with the combination of ENT plus VCR reduced tumor volume significantly." (PMID 31113472, 2019). "Several of these models have attempted to constitutively express PAX3/7-FOXO1 fusion proteins in the skeletal muscle lineage during development, only to result in developmental defects and not tumor formation." (PMID 23206814, 2012). "Among the ERMS and ARMS, there was no clear pattern for wild-type PAX3 mRNA expression, detected in 16 out of 30 primary ERMS and ARMS tumour samples, nor was there any correlation with the presence of PAX3/7-FKHR fusion genes." (PMID 12865925, 2003). "Expression levels were quantified relative to expression in the RD cell line (RDCL) for PAX3 and PAX7, the Rh30 cell line for PAX3-FKHR and a primary tumour (sample 6) for PAX7-FKHR, since no cell line expressing this fusion gene was available." (PMID 12865925, 2003). "In RMS, major characteristic of tumour aggressiveness is represented by the PAX3/7-FOXO1 fusion gene, a negative prognostic factor that regulates transcription of several downstream tumour-driving genes, including c-Met, CXCR4, FGFR4, IGFR-1R and PDGFRα kinases." (PMID 26147305, 2015). "We used this technique to measure mRNA levels for wild-type PAX3, PAX7, PAX3-FKHR and PAX7-FKHR in RMS, to determine whether higher levels of wild-type PAX3 and PAX7 are observed in tumours that do not express PAX3-FKHR and PAX7-FKHR chimaeric transcripts." (PMID 12865925, 2003).
tumor (continued). "Notably, and unlike PAX3::FOXO1-driven tumors, tumorigenesis was significantly more efficient in P0 animals, where even the fusion alone (+ sg-empty) led to tumors with 100% penetrance, albeit with mean latencies of about 230 days and 37% bilateral tumor fraction." (PMID 40523919, 2025).
cancer (44 papers, 2006 to 2026). A tumor composed of atypical neoplastic, often pleomorphic cells that invade other tissues. "Alterations in the activity of the PAX3 gene are associated with some cases of cancer in muscle tissues." (PMID 23285167, 2012). "a highly aggressive childhood muscle-derived cancer in which the oncogenic fusion protein paired box 3–forkhead box O1 (PAX3-FOXO1) stimulates the RASSF4 protein expression." (PMID 41007433, 2025). "The enhanced expression of PAX3 or PAX7 in ARMS–here as a fusion protein–is reminiscent of MuSCs in cancer cachexia which are also displaying aberrant high levels of Pax7 expression." (PMID 39050890, 2024). "Investigating the mechanisms related to the cellular activity of FOXO1 and PAX3 will likely contribute to the development of cancer therapies." (PMID 31823759, 2019). "Transcription factors forkhead box protein O1 (FOXO1) and paired box 3 (PAX3) have been reported to play important roles in various cancers." (PMID 31823759, 2019). "The expression of the muscle transcription factor Pax3 was significantly higher in both cancer groups and HE compared with HMA." (PMID 27454226, 2016). "The pathways that PAX3 regulates during development may be recycled and subverted during disease progression, for example, during cancer progression, growth, and metastasis." (PMID 41897383, 2026). "The aberrant expression of Pax7 or Pax3 might be one of the main drivers of impaired myogenic differentiation in ARMS as observed in MuSCs in cancer cachexia." (PMID 39050890, 2024). "The KDM3A and Ets1 upregulated transcriptomes, alone and together, also contain numerous additional genes implicated in cancer promotion, which are not dependent on PAX3/FOXO1 for expression." (PMID 32697014, 2020). "Thus, the surprisingly dynamic regulation of the Pax3:Foxo1a locus is a paradigm that has important implications for the way in which oncogenes are modeled in cancer cells." (PMID 24453992, 2014). "As PAX3 is predominantly expressed during embryogenesis and in malignant cells, and is absent in differentiated tissues, anti-PAX3 therapies might selectively target cancer cells, thus avoiding toxicity to normal cells." (PMID 24188742, 2014). "In ARMS, up to 80% of cases are characterized by a chromosomal translocation resulting in the formation of PAX3/FOXO1 or PAX7/FOXO1 fusion onco-proteins, key markers of poor prognoses in these cancers." (PMID 37858275, 2023). "Genome-wide ChIP-seq analysis reveals that the boundaries of decreased H3K9me2 large organized chromatin K9 modifications (LOCKs) are enriched with cancer-related genes, such as MYC and PAX3." (PMID 27034728, 2016). "In an analysis of 24 breast tumours, rearrangements were found in known cancer genes including BRAF, PAX3, PAX5, NSD1, PBX1, MSI2 and ETV6, each of which is a partner in a fusion gene in several other human cancers." (PMID 24792170, 2014).
cancer (continued). "Moreover, our network analysis indicated alterations in MAPK/ERK and Jun-N-terminal kinase pathways and the potential important role of PAX3, VCAN, ARRB2, NR1H2, and ITGA5 that may provide insights into mechanisms involved in longevity and regeneration that are distinct from cancer." (PMID 22477361, 2013). "However, nearly twice as many 4N cells are Igf1r (or Pdgfra) positive versus Igf1r (or Pdgfra) negative, suggesting these Pax3:Foxo1a targets may have a functional role late in the cell cycle, such as the Igf1r-mediated radioresistance seen for other forms of cancer." (PMID 24453992, 2014).
infection (4 papers, 2009 to 2021). The state of being infected such as from the introduction of a foreign agent such as serum, vaccine, antigenic substance or organism. "Ad‐Pax3 Infection for 48h resulted in a significant decreased number of proliferating Neuro‐2a cells." (PMID 33336498, 2021). "Western blotting of cell lysates confirmed that infection of cells with Pax3 or Pax7 RV resulted in an increase in MyoD protein, whereas infection with retroviruses encoding Pax3DN or Pax7DN resulted in a decrease in MyoD protein." (PMID 19221588, 2009). "After infection, we obtained two groups, overexpressing Pax3 and Pax7 (mark as OEPax3 and OEPax7)." (PMID 33336498, 2021). "Indeed, we found that co-infection of Nkx3.2ΔC-VP16 with Sox9 completely abolished the ability of Sox9 to inhibit Pax3 and MHC expression." (PMID 22768305, 2012). "It is therefore likely that in adult muscle progenitor cells, there is significant overlap between Pax3 and Pax7 target gene selection, explaining the similar outcomes of infection with Pax3 and Pax7 RV and of inhibiting target gene transcription using the dominant-negative versions." (PMID 19221588, 2009). "In contrast to the ability of ectopic PAX3-FOXO1A, Pax3 and Pax7 were unable to induce each other, or myogenic proteins, in NIH 3T3 fibroblasts maintained under expansion conditions (although specific culture conditions can produce limited activation of the myogenic program after Pax3 infection)." (PMID 19221588, 2009). "Infection of the human melanocyte line Hermes 3A with shATF2 effectively inhibited ATF2 expression, upregulated Mitf transcription and increased transcription of SOX10 and FOXD3 (from 7- to 10-fold) and to a lesser extent of Pax3 and Brn2 (from 1.5- to 2-fold)." (PMID 21203491, 2010). "Infection of C2C12 cells or satellite cell-derived myoblasts with Pax3 RV or Pax7 RV did not prevent the development of multinucleate myotubes, though in both cases there was a slight delay (∼24 h) in fusion." (PMID 19221588, 2009).
head and neck tumors (2 papers, 2013 to 2024). "PAX3::FOXO1 inhibits the Hippo/MST1 signaling pathway, and genetic removal of Mst1/Mst2 Hippo pathway members in the Myf6-Cre Pax3::Foxo1 mouse model increased the frequency of head and neck tumors." (PMID 38916046, 2024).
myopathy (2 papers, 2017 to 2020). A disease of the muscle in which the muscle fibers do not function properly. "A higher level of PAX3 expression was also observed in the muscles of patients carrying loss of function mutation in PAX7 gene, leading to a myopathy of variable severity." (PMID 32552916, 2020). "Interestingly, the induction of SYT-SSX expression through Hprt-Cre, Pax3-Cre, or Pax7-Cre resulted in embryonic lethality, and SYT-SSX expression in Myf6-expressing myocytes or Myf6-expressing myofibers resulted in myopathy but no tumors." (PMID 27191748, 2017).
autosomal dominant disease (1 paper, 2011). Autosomal dominant form of disease. "This could explain why the WS PAX3 alleles, which appear to be loss-of-function mutations, cause an autosomal dominant disease." (PMID 22216266, 2011).